TLR4 (toll like receptor 4)
Diseases named in the same sentence as TLR4 in open-access papers (continued):
Sharing a sentence is not in itself a finding about the gene and the disease.
tumor (continued). "Activation of the TLR4/COX-2/prostaglandin E2 (PGE-2) pathway inhibits the secretion of anti-tumor immune cytokines, suppresses tumor cell apoptosis, and augments tumor occurrence." (PMID 38930793, 2024). "Mechanistically, in chimeric and conditionally targeted PDAC mouse models, myeloid-specific TLR4 signaling executes the MyD88-independent TRIF pathway to promote tumor growth, whereas MyD88-dependent signaling inhibits tumor growth." (PMID 38390872, 2024). "In response to Toll-like receptor 4 (TLR4) stimulation, HBx is involved, the retain of the BECN1-Bcl-2 complex and the boost of the TRAF6-BECN1-VPS34 complex, thus enhancing tumor progression." (PMID 38464387, 2024). "When LPS binds to TLR4 in gastric epithelial cells, TLR4 signaling is activated, which leads to the production of inflammatory mediators including IL-8 and TNF-α, which are essential for the progression of tumor." (PMID 39035439, 2024). "Cell-free supernatant from CRC cells after chemotherapy induces DC phenotypic maturation through Toll-like receptor 4 (TLR4) and enhances anti-tumor immune responses in CRC-bearing mice." (PMID 39262952, 2024). "Thrombospondin 2 activation of TLR4 enhances HIF‐1α‐mediated glycolysis and promotes tumor growth in CRC." (PMID 38685971, 2024). "Activation of the TLR4/NF-κB signaling pathway triggers apoptotic cascades, selectively decreasing MDSC percentages in tumor-bearing mice spleens." (PMID 38930793, 2024). "Tumor patients showing Cyto-HMGB1 translocation and PD-1+tumor-infiltrating lymphocytes (TILs) pre-treatment exhibit better clinical outcomes, possibly due to HMGB1 release inducing DC maturation via TLR4 activation." (PMID 38930793, 2024). "Through a toll-like receptor 4 (TLR4)-dependent pathway, ETBF increases levels of transcriptional and epigenetic regulators, which promote tumor growth both in vivo and in vitro." (PMID 39676876, 2024). "Surprisingly, we found that blocking the extracellular TLR4 signaling from S100A9 using the inhibitor Paquinimod, resulted in increased tumor growth and a detrimental effect on anti-PD-L1 efficacy in the CT26 tumor model." (PMID 39497822, 2024). "explored the landscape of TLR expression in the tumor microenvironment of triple-negative breast cancer (TNBC), identifying distinct roles of TLR4 and TLR8 in the maintenance of the tumor-immune microenvironment." (PMID 38903515, 2024). "TLR4 responds to stimulation to activate signaling pathways, such as AMPK, and also regulates the tumor microenvironment, thereby influencing tumor progression." (PMID 38799454, 2024). "TLRs, such as TLR4/TLR5, are typically activated by bacterial components, including LPS and flagellin, to exert anti‐tumor immunity." (PMID 38888519, 2024). "It is safe at therapeutic doses and efficiently inhibits NF-κB, showing potent anti-tumor effects on CRC by suppressing cell viability, inducing apoptosis, and modulating the TLR4/NF-κB pathway." (PMID 38930793, 2024). "It has been demonstrated that Toll-like Receptor4 (TLR4) can participate in signaling, such as NF-B and NLRP3, to facilitate tumor metastasis." (PMID 39494337, 2024). "Tasquinimod (oral treatment, day 0 or 1 to end of experiment), q-compound targeting TLR4 signaling of S100A9, alone, with SurVaxM peptide and GM-CSF or with tumor-targeted superantigen." (PMID 39497822, 2024). "We further emphasize the involvement of TLR4 signaling in CRC initiation and progression by elucidating its roles in various phenotypes such as proliferation, metastasis, and tumor immune microenvironment." (PMID 38930793, 2024). "These microbes activate the TLR4/MyD88 pathway in CRC, contributing to the delta-5 desaturase-arachidonic acid axis, metabolizing to PGE-2, and ultimately encouraging tumor growth." (PMID 38930793, 2024). "TLR-4 and TLR-2 have shown superior tumor antigen recognition patterns and the capacity to trigger innate and acquired immune responses in the ten types of TLRs (Toll-like receptors)." (PMID 39050853, 2024).
tumor (continued). "Within the tumour microenvironment, NY‐ESO‐1, released from necrotic cancer cells, engages with complement C1q receptor and Toll‐like receptor 4 (TLR4) on the surface of immature dendritic cells (DCs)." (PMID 39275923, 2024). "In contrast, tumor cells often exhibit overexpression of specific TLRs, such as TLR2, TLR4, and TLR9." (PMID 39640496, 2024). "Researchers further found that HMGB1 was released by tumor cells after radiation therapy, and HMGB1 promoted NET formation by activating TLR4 signaling." (PMID 36993957, 2023). "ENO1 orchestrated the IL-6 secretion of macrophages via tumor cell-derived lactic acid and the paracrine ENO1/Toll-like receptor (TLR4) signaling pathway." (PMID 36614179, 2023). "These cationic polymers activated the TLR-4 signaling pathway, resulting in TLR-4 dimerization, acute inflammation, and direct tumor cell killing, thereby prolonging the survival time of mice, and inhibiting tumor growth and metastasis." (PMID 37103820, 2023). "Comparable anti-tumor results were detected in mice models of Lewis lung carcinoma and sarcoma following induction of TLR3 and TLR4 mediated signaling, respectively." (PMID 37936697, 2023). "S100A8, an endogenous ligand of Toll-like receptor 4 (TLR4), is known as a key molecule in the tumor microenvironment and premetastatic niche formation." (PMID 36932197, 2023). "As most tumor cells including SW480 cells also express TLR4, S100A8 inhibitory peptides would target both the tumor microenvironment and tumor cells." (PMID 36932197, 2023). "Further investigation demonstrated that arctiin suppresses inflammation, fibrosis, and tumor cell migration by inhibiting STAT3, TGF-β1, TLR4, NLRP3, VEGF, and cyclin D1." (PMID 37701157, 2023). "TLR4 signaling plays a critical role in promoting the formation of NETs in HCC cells, which intriguingly contributes to the promotion of tumor growth and metastasis." (PMID 37345131, 2023). "We previously reported that Eritoran, a TLR4 inhibitor, inhibited S100A8-mediated cell migration and tumor progression in tumor-bearing mice." (PMID 36932197, 2023). "Among all TLR2, TLR4, and TLR5 subgroups and the positive TLR7 subgroup, patients with a low CD3–CD8 tumor–stroma index exhibited a worse survival." (PMID 36649244, 2023). "For example, certain antitumor microorganisms such as Bacteroides thetaiotaomicron and B. fragilis can activate DCs through TLR-4 signaling, promote Th1 and cytotoxic CD8+ T-cell responses, and help tumor immune surveillance and eradication." (PMID 37691931, 2023). "According to the current studies, there are 7 HA receptors, CD44, RHAMM, TLR2, TLR4, LYVE, LAYN and STAB2, which participate in connecting extracellular signal and intracellular signalling in tumor diseases." (PMID 36698043, 2023). "TLR4 has also been detected (at mRNA and protein levels) in distinct PCa cell lines (DU145 and PC-3) and tumor samples, despite at significantly lower levels as compared with BPH tissue." (PMID 37819510, 2023). "The activation of TLR4/NF-κBp65/COX-2 signaling in HCC cells trapped by NETs promotes angiogenesis and tumor cell migration, inducing a pro-metastatic phenotype." (PMID 37345131, 2023). "Additional research has shown that arctiin is able to suppress inflammation, fibrosis, and the migration of tumor cells by inhibiting STAT3, TGF-β1, TLR4, NLRP3, VEGF, and cyclin D1." (PMID 37701157, 2023). "Knockout or inhibition of CXCL10/TLR4 significantly reduced the M-MDSC levels and constrained tumor growth in a mouse recurrent tumor model." (PMID 36911674, 2023). "According to one study, Fusobacterium nucleatum enhanced tumor cell miR-21 levels by turning on the TLR4-MyD88 signaling cascade, which in turn increased CRC cell growth and tumor development in mice." (PMID 36762108, 2023). "HMGB1, while being dependent on Toll-like receptor 4 (TLR4), also improves antigen cross-presentation by DCs, hence leading to an adaptive immune response against the tumor." (PMID 37857049, 2023).
tumor (continued). "MSCs that have been primed with TLR4 are referred to as MSC1 and display an antitumorigenic effect, while MSCs that have been primed with TLR3 are known as MSC2 and have a tumor-supportive role." (PMID 37849741, 2023). "Both in vitro and in vivo experiments demonstrated that BGN promoted tumor progression and transformation of MCs into CAFLCs through the TLR2/TLR4/NF-κB signaling pathway." (PMID 36632455, 2023). "The activation of T-reg cells by engaging TLR4 in patients with HNSC has the potential to bolster the inhibitory capabilities of T-reg cells., thereby potentially contributing to tumor-induced immune suppression." (PMID 37926766, 2023). "The M1 macrophages, occurring after toll-like receptor 4 (TLR4) ligands and/or IFN-γ exposure, is pro-inflammatory and anti-tumor." (PMID 37818357, 2023). "Altogether, these data shed light on the role of tumor-produced PTX3 in TNBC and uncover the importance of the PTX3/TLR4 axis for therapeutic and prognostic exploitation in TNBC." (PMID 37749607, 2023). "In fact, among cytokines released upon TLR-4 activation, TGFβ, VEGF, CCL-2 and IL-10 can induce CD4+CD25+Foxp3+ regulatory T cells (Tregs), which exert an immunosuppressive effect in the tumor microenvironment." (PMID 36838231, 2023). "LMW-HA induces the secretion of inflammatory factors, matrix hydrolases and pro-angiogenic factors by activating the specific receptors such as TLR2, TLR4, and LAYN of tumor cells, which dominates in the field of metastasis and colonization." (PMID 36698043, 2023). "In vitro experiments demonstrated that BGN promoted tumor progression and transformation of MCs into CAFLCs by TLR2/TLR4/NF-κB signaling pathway." (PMID 36632455, 2023). "Representative IHC staining of KLF7, TLR4, and PTK2 in HCC tissues and adjacent non-tumor tissues is presented." (PMID 37554278, 2023). "The interaction between extracellular HMGB1 and TLR4 correlates with ICD, and the depletion of TLR4 and the depletion or neutralization of HMGB1 can eliminate the cross-presentation of tumor antigens by DCs." (PMID 36906586, 2023). "Reduced expression of eight immune‐related genes (IRGs) (NT5E, THRA, RBP1, TLR4, ITGA6, BMPR1B, ITGAV, SSTR1) in tumor strongly predicted better quality of prognosis, both in our patient cohort and in TCGA‐HNSC cohort." (PMID 37392167, 2023). "Collectively, PepO provoked M2 macrophages to polarize toward the anti-tumor M1 phenotype, which was dependent on both TLR2 and TLR4." (PMID 37925462, 2023). "TLR2, TLR4, and inflammasome inducing MR, NLRP3 can lead to tumor progression via the production of inflammatory cytokines (IL6, IL16), increased cell proliferation, and resistance to apoptosis (TNFAIP3)." (PMID 37599366, 2023). "TLR4, which is expressed on CRC cells, is activated by Clostridia, making these tumor cells more resistant to oxaliplatin-induced cell death." (PMID 37691931, 2023). "TLR4 signaling can also promote the recruitment of immune cells in the TME, such as T cells and DCs, which can enhance the anti-tumor immune response." (PMID 37345131, 2023). "CXCL10, P2RX7, TLR3, and TLR4 were significantly upregulated in IS2 tumours in the TCGA cohort, whereas ANXA1, CXCL10, FPR1, IFNAR2, P2RX7, and TLR4 showed significantly higher expression levels in IS4 tumours in the GEO cohort." (PMID 36851274, 2023). "For instance, the activation of TLR4 (Toll-like receptor 4) on HGOS cells dramatically increases CD8+ TILs and reduces both tumor growth and lung metastasis in immunocompetent mice, improving the HGOS outcome." (PMID 36614241, 2023). "CDK1, ECT2, EZH2, GJB2, GPR37, GPX2, and GPX8 mRNA expression was up-regulated in the tumor group (p < 0.001), whereas GPX3, HYAL1, and TLR4 mRNA expression was down-regulated in the tumor group (p < 0.001) compared with those in the normal group." (PMID 37689745, 2023).
tumor (continued). "It has been reported that S100A8 upregulated PD-L1 in macrophages via a TLR4-dependent pathway, and we previously found that the inhibition of TLR4 by Eritoran increased intratumoral infiltration of CD8+ cells in LLC-tumor-bearing mice." (PMID 36932197, 2023). "More importantly, increasing studies demonstrated that F. nucleatum contributes to the change of tumor microenvironment and the progression of CRC via a TLR4-dependent mechanism." (PMID 37221488, 2023). "Toll-like receptor 4 (TLR4), a molecule that participates in the tumor microenvironment (TME), showed a similar expression trend." (PMID 36831377, 2023). "SP via NK1R upregulated toll-like receptor-4 (TLR-4) and contributed to the increase of tumor cell biological activity." (PMID 37215113, 2023). "Despite the fact that there are a great number of TLR4 activators in the TME, there is limited evidence supporting the link between tumor-derived paracrine ENO1 and TLR4 expression." (PMID 36614179, 2023). "Tumor-derived exosomes induce proinflammatory cytokine expression and PD-L1 regulation in M0 macrophages through IL-6/STAT3 and TLR4 signaling pathways." (PMID 36176299, 2022). "After ICD development in tumor cells, HMGB1 acts on TLR4 on DC and promotes optimal processing of tumor antigen toward crossover triggering T cells." (PMID 36212143, 2022). "For example, HMGB1 acts through TLR4/TLR9 receptors and activates tumor cells via the p38/NFkB pathway." (PMID 36555469, 2022). "Some researchers found TLR4 was down-regulated in UBC tissue compared to normal tissue and surrounding tumor." (PMID 36230476, 2022). "Our previous work had reported that SEP activated NK cells to kill tumor cells via both TLR2 and TLR4 signaling pathways." (PMID 35370674, 2022). "Lymphocyte antigen 96 (LY96 or MD2), which is from the toll-like receptor 4 (TLR4) signaling pathway, promotes the development of immunotherapy and targeted therapy of malignancies in tumor occurrence and progression." (PMID 36429083, 2022). "This engineered virotherapy has also been applied to autologous tumor vaccines including GVAX (GM-CSF), FVAX (FLT3L), and TEGVAX (GM-CSF, TLR4 agonist, and TLR7/8 agonist)." (PMID 36031601, 2022). "Blood LPS levels and downstream signaling molecule TLR4, COX-2, and p-STAT3 protein expression levels were reduced, which correlated with tumor drug resistance and invasion capabilities." (PMID 36267958, 2022). "CTP enhances the levels of TLR4 and TLR5 in ApcMin/+ mice, indicating an enhanced tumor killing response mediated by T cells." (PMID 35662701, 2022). "CD91, toll-like receptor 4 (TLR4), and The P2X7 receptor (P2RX7) are expressed by dendritic cells (DCs) and promote phagocytosis of dead cells, presentation of tumor antigens, and production of IL-1β, respectively." (PMID 36081554, 2022). "By contrast, the roles of the coreceptor of TLR4, MD2, in tumor progression remain poorly understood." (PMID 35372062, 2022). "We measured TLR9, 2 and 4 expressions in our tumor samples and classified our cohort of patients as showing high (≥2) or low (<2) score expression levels of TLR9 (n=22), TLR2 (n=28) and TLR4 (n=29)." (PMID 35990685, 2022). "Previous evidence from preclinical models and tumor tissues support that TLR4 and STAT3 signaling pathways cooperate on cancer cells to promote EMT, stemness, tumor growth, and immunosuppression." (PMID 35205801, 2022). "The cross talk between TLR4/NF-κB and HIF-1α signaling pathway forms a positive feedback loop and contributes to tumor initiation, malignant progression, and prognosis in EOC." (PMID 35464826, 2022). "To evaluate the effect of both compounds on genes/proteins previously demonstrated to be important in the tumor–macrophage interaction, we also evaluated the gene expression of CD274 (Pdcd1, PD-L1), TLR4, BMPR2 and miR-21 by RT-qPCR on the treated cell lines." (PMID 35053451, 2022).
tumor (continued). "The authors reported efficient tumor elimination at effector:target ratios of 1:10 (TLR2 and TLR4 MOTO-CARs), 1:5 (TLR4 MOTO-CAR), and 2:1 (TLR2 and TLR4 MOTO-CARs), compared to non-transfected macrophages (mock) controls." (PMID 35884798, 2022). "We also investigated expression changes in TLR4, NF-κB, and STAT3 in tumor tissue and explored the impact of bacterial flora alterations." (PMID 36267958, 2022). "Upon testing the effect of MOTO-CARsTM on tumor burden in NSG mice containing HCC-1806-derived xenografts, they observed a 46% decrease in tumor weight in TLR4 MOTO-CAR treated mice compared to mock mice." (PMID 35884798, 2022). "The S100 protein family members, S100A8A/S100A9, which form an S100A8/A9 heterodimeric complex able to interact with both TLR4 and RAGE on tumor cells, are also key in promoting RAGE-mediated inflammatory responses." (PMID 35727208, 2022). "In a direct manner, platelet receptors like αIIbβ3 and αVIβ1 can bind to tumor αVβ3 and ADAM9 respectively, as well as binding with P-selectins through PSGL-1 interaction, platelet toll-like receptor 4 and facilitating CLEC2-podoplanin interactions." (PMID 35163180, 2022). "The FnBPA antibody also significantly decreased the activation of the c-fos and NF-κB caused by MRSA indicating that MRSA upregulated the fnbpA to activate TLR4/NF-κB/p38 MAPK/c-fos signaling pathway and then to increase the proliferation of tumor cells." (PMID 35859766, 2022). "S100A8/A9 promotes tumor development and invasiveness by increasing leukemic cell growth through RAGE and secretion of pro-inflammatory cytokines through the TLR4-NFκB pathway." (PMID 35586193, 2022). "In vivo assays revealed that mouse tumor growth and ER stress inhibited by KGM and 5-FU cotreatment were rescued after TLR4 upregulation." (PMID 37304412, 2022). "Besides, some of the immune-related factors associated with tumor invasion and metastasis such as HMGB1 and Toll-like receptor 4 (TLR4) play a considerable role in rebuilding TIM and promoting the development of pyroptosis that could also be upregulated by hypoxia." (PMID 36204682, 2022). "Radiotherapy can lead to ICD and the release of high migration group box 1 protein (HMGB-1); HMGB-1 binds to Toll-like receptor-4 (TLR-4), participates in the progression and presentation of tumor antigens, and promotes the activation and maturation of DCs." (PMID 35935943, 2022). "Previous studies have shown that multiple PRRs (TLR2, TLR3, TLR4, TLR7, TLR8 and RIG‐1) in stromal cells recognise tumour cell‐derived EVs and participate in tumour metastasis." (PMID 36068649, 2022). "In summary, some key genes were identified by a variety of bioinformatics methods in this study and the roles of a few genes have been deeply studied in tumor biology, such as FPR2 and TLR4." (PMID 35675043, 2022). "The protein expression of p-PERK, ATF4 and CHOP in mouse tumor tissues was evaluated, and the KGM+5-FU-induced elevation in the protein levels of p-PERK, ATF4 and CHOP was reversed after TLR4 upregulation." (PMID 37304412, 2022). "A growing body of evidence suggests a link between TLR4 and pSTAT3—more particularly, TLR4 signaling activates and cooperates with STAT3, to induce the formation of EMT-like CSCs and to promote tumor growth and immunosuppression." (PMID 35205801, 2022). "We then evaluated the expressions of all TLRs in KIRC tumor tissues by GEPIA and found that TLR3 was particularly highly expressed in KIRC, followed by TLR4 and TLR2, which was consistent with the results of UALCAN database." (PMID 35127830, 2022). "Specifically, F. nucleatum can activate TLR4 signaling to promote tumor development, and another over-presented bacterium, Peptostreptococcus anaerobius, can promote carcinogenesis by activating TLR2 and/or the TLR4 pathway in patients with CRC." (PMID 36465375, 2022).